MSTN (myostatin)
Diseases named in the same sentence as MSTN in open-access papers (continued):
Sharing a sentence is not in itself a finding about the gene and the disease.
Hyperinsulinemia (6 papers, 2020 to 2025). An increased concentration of insulin in the blood. "In the context of IR, compensatory hyperinsulinemia occurs, leading to reduced suppression of glycogenesis, accelerated protein catabolism, decreased protein anabolism, and increased myostatin levels." (PMID 39125348, 2024). "Hyperinsulinemia has been shown to increase the amount of serum myostatin, which acts to negatively regulate the skeletal muscle growth." (PMID 32781673, 2020).
limb-girdle muscular dystrophy (6 papers, 2007 to 2020). Limb-girdle muscular dystrophy (LGMD) is a heterogeneous group of muscular dystrophies characterized by proximal weakness affecting the pelvic and shoulder girdles. "The use of neutralizing antibodies to myostatin improved muscle disorders in rodent models of DMD (mdx) and limb-girdle muscular dystrophy 2f (Sgcg−/−)." (PMID 25221510, 2014).
pancreatic cancer (6 papers, 2017 to 2025). "Anti-myostatin antibodies are expected to treat muscle loss, but one of the antibodies, LY2495655, did not improve muscle mass and function at least in pancreatic cancer." (PMID 38804293, 2024). "Pertinently, the MSTN neutralizing antibody LY2495655 did not improve survival in a Phase 2 trial of 125 patients with stage 2–4 pancreatic cancer, and indeed treatment trended poorer survival." (PMID 33334063, 2020).
renal failure (6 papers, 2013 to 2025). "Myostatin and activin A, which binds to the myostatin receptor, have been linked to muscle atrophy and are upregulated in renal failure." (PMID 23431467, 2013). "Myostatin is increased in renal failure and other cachexia-related disease states." (PMID 23431467, 2013).
Stroke (6 papers, 2017 to 2025). Sudden impairment of blood flow to a part of the brain due to occlusion or rupture of an artery to the brain. "This could be due to intramuscular fat accumulation, consequent to stroke, that may cause insulin resistance, and the subsequent hyperinsulinemia has been shown to increase serum myostatin." (PMID 35002937, 2021). "We previously showed that expression of myostatin, a master negative regulator of skeletal muscle mass, was strongly increased in skeletal muscle in a mouse model of stroke." (PMID 29070788, 2017). "Therefore, an anti-myostatin strategy can improve skeletal muscle recovery after cerebral ischemia and may thus represent an interesting strategy to combat skeletal muscle loss and weakness in stroke patients." (PMID 29070788, 2017). "Overall, these data illustrate the efficiency of an anti-myostatin strategy in this mouse model of stroke." (PMID 29070788, 2017). "In the present study, we report the effect of an anti-myostatin strategy on the regulation of skeletal muscle mass and function in a mouse model of stroke." (PMID 29070788, 2017). "Thus, our findings suggest that an anti-myostatin strategy represents a potential therapeutical approach to limit the deleterious effects of stroke on skeletal muscle mass and function." (PMID 29070788, 2017). "Muscle is involved in maintaining the bone mineral content and in electrical muscle stimulation following sciatic neurectomy in rats; muscle fibers downregulated myostatin gene expression, a model that should suggest the downregulation of this myokine in stroke-derived paretic limbs." (PMID 28373915, 2017). "This evidence may suggest even a role of myostatin as a prognostic marker for stroke." (PMID 28373915, 2017). "However, the question whether myostatin inhibition could be used as therapeutical intervention in stroke remains unanswered." (PMID 29070788, 2017). "In summary, our data provide evidence that a short-term treatment with a myostatin inhibitor (PINTA745) can increase body weight recovery and skeletal muscle mass in a mouse model of stroke." (PMID 29070788, 2017). "In the present study, we therefore determined the potential therapeutic impact of myostatin inhibition in a mouse model of stroke by administration of PINTA745, a genetically engineered myostatin-neutralizing peptide fused to a Fc fragment." (PMID 29070788, 2017). "This was supported by an increase in MSTN expression in the skeletal muscle of the paretic limb compared to the non-paretic limb in stroke patients." (PMID 35395053, 2022). "In support of this assumption, myostatin expression has been shown to be elevated in skeletal muscles of the paretic limb compared to the non-paretic limb of stroke patients." (PMID 29070788, 2017). "Moreover, it was demonstrated that the expression levels of myostatin mRNA, which downregulate the skeletal muscle growth, are 40% higher in the paretic than non-paretic muscles in stroke survivors." (PMID 35002937, 2021).
breast carcinoma (5 papers, 2015 to 2025). "In breast cancer, elevated myostatin expression has been associated with better prognosis and overall survival, so further research is required to clarify this association and determine its clinical relevance." (PMID 40806072, 2025). "Although there is little evidence that myostatin or GDF-9 is expressed in breast cancer, inhibition of the BMP receptor, activin receptor-like kinase 2 (ALK2), can reduce metastatic spread of mammary tumors in mice." (PMID 28583174, 2017).
ischemia (5 papers, 2016 to 2023). A hypoperfusion of the BLOOD through an organ or tissue caused by a PATHOLOGIC CONSTRICTION or obstruction of its BLOOD VESSELS, or an absence of BLOOD CIRCULATION. "Such a shift in the myostatin/follistatin balance might indicate a reduction in the role of myostatin during recovery from the post-ischemia/reperfusion injury." (PMID 38136649, 2023). "However, it does agree with the increase of myostatin in the heart muscle induced by ischemia." (PMID 28217409, 2016). "Our results thus confirm that myostatin and its close homolog GDF11 are differently expressed in the heart in response to ischemia and indicate that they may participate in different processes." (PMID 30765322, 2019).
lung carcinoma (5 papers, 2016 to 2023). "Conversely, in non-weight losing patients with gastric cancer, but not those with lung cancer, expression of myostatin has been found to be significantly higher." (PMID 36269458, 2022). "Of note, also the expression levels of other putative tumor-derived cachexia-inducing signaling compounds (OSM, LIF, TNFα, IFNγ, PTHrP, ZAG, PIF, TWEAK, IL-1β, MSTN and INHBA) were tested for possible correlation between expression level and prognosis for lung cancer patients." (PMID 28515477, 2017). "Interestingly, in the same study, lung cancer patients had no increase in myostatin serum levels but did have increases in Smad2 expression, raising the question whether different tumors might induce different patterns of molecular changes within skeletal muscle tissue." (PMID 26856534, 2016).
preeclampsia (5 papers, 2020 to 2022). Preeclampsia is a hypertensive disorder of pregnancy that is characterized by new-onset hypertension with proteinuria presenting after 20 weeks of gestation, and depending on mild or severe forms may initially present with severe headache, visual disturbances, and hyperreflexia. "MSTN, a negative regulator of muscle development, may also be involved in cytokine production and glucose metabolism, and has been associated with preeclampsia and IUGR in human pregnancies." (PMID 34299281, 2021). "Maternal serum levels and placental expression of FSTL3 and MSTN were found to be considerably higher in women with preeclampsia." (PMID 35780124, 2022). "Another study found that variations in MSTN concentration in plasma can be detected early in preeclampsia and intrauterine growth restriction (IUGR) and PE-IUGR pregnancies, with increased expression of MSTN in presymptomatic PE plasma." (PMID 35780124, 2022). "A study on the expression of myostatin in preeclampsia revealed elevated levels of myostatin in the plasma of women who later developed this disorder, which can suggest the potential usage of plasma myostatin as biomarker in preeclampsia." (PMID 32796600, 2020). "The dynamic change in myostatin is more than that in FSTL3 in women with preeclampsia." (PMID 36325361, 2022). "The TGF-β family member, myostatin, is highly expressed in patients with preeclampsia." (PMID 36325361, 2022). "Furthermore, findings from clinical samples suggest that MSTN may play a key role in the pathogenesis of several reproductive disorders such as uterine myoma, preeclampsia (PE), ovary hyperstimulation syndrome (OHSS), and polycystic ovarian syndrome (PCOS)." (PMID 35780124, 2022). "Many studies have shown that MSTN and FSTL3 may have a role in the regulation of normal placentation and preeclampsia." (PMID 35780124, 2022).
rhabdomyosarcoma (5 papers, 2015 to 2022). A rare aggressive malignant mesenchymal neoplasm arising from skeletal muscle. "KMM001 inhibited SMAD-mediated myostatin signaling in rhabdomyosarcoma cells." (PMID 35563408, 2022). "In a reporter-gene assay conducted with a human rhabdomyosarcoma (A204) cell line, ACE-083 inhibited signaling by activin A, activin B, myostatin and GDF11 in a dose-dependent manner, with IC50 values ranging from approximately 40–700 pM or, in alternative units, 5–80 ng/mL." (PMID 31388039, 2019). "In the current study, we revealed that the inhibitory core of the myostatin prodomain (42CTWRQNTKSSRIEAIKIQILSKLRLETAP70) resides near its N-terminus by expressing various prodomain regions as Fc fusion proteins in both HEK293 embryonic kidney cells, or A204 rhabdomyosarcoma cell." (PMID 26226340, 2015).
gastric cancer (4 papers, 2016 to 2022). A primary or metastatic malignant neoplasm involving the stomach. "Conversely, in those very same studies showing elevated activin A, circulating myostatin was found decreased, similar to myostatin gene expression in gastric cancer patients with minimal or no weight loss." (PMID 33671024, 2021).
hepatocellular carcinoma (4 papers, 2020 to 2024). A malignant tumor that arises from hepatocytes. "Among patients with similar residual liver function or similar risk of developing hepatocellular carcinoma using other models, higher serum myostatin was significantly associated with a higher risk of developing hepatocellular carcinoma." (PMID 33198216, 2020). "We found that serum myostatin is associated with hepatocellular carcinoma development in a large cohort of patients with alcoholic cirrhosis." (PMID 33198216, 2020). "Thus, serum myostatin as a prognostic marker can be useful to identify high-risk patients who need stringent surveillance for hepatocellular carcinoma." (PMID 33198216, 2020). "We aimed to elucidate the association between serum myostatin levels and hepatocellular carcinoma (HCC) development in patients with alcoholic liver cirrhosis (ALC)." (PMID 33198216, 2020). "As myostatin was elevated in the gastrocnemius muscle of mice inoculated with the Yoshida AH-130 hepatoma, targeting the myostatin pathway seemed promising in preventing cancer cachexia." (PMID 33802348, 2021). "In alcoholic cirrhotic patients, the incidence of hepatocellular carcinoma (HCC) was shown to be significantly higher in patients with higher serum myostatin levels compared to those with lower serum myostatin levels (hazard ratio (HR) = 7.53)." (PMID 38256036, 2024). "In this study, we aimed to evaluate whether serum myostatin is associated with hepatocellular carcinoma development in patients with alcoholic cirrhosis or not." (PMID 33198216, 2020).
hypertrophic cardiomyopathy (4 papers, 2015 to 2024). A condition in which the myocardium is hypertrophied without an obvious cause. "The cats with hypertrophic cardiomyopathy or hypertrophicobstructive cardiomyopathy exhibited higher myostatin levels than those withcongestive HF." (PMID 39077334, 2024). "The novel up-regulated genes were related to hypertrophic cardiomyopathy, focal adhesion, and PA signaling pathway, and ROS removal processes, suggesting that myostatin directly affects these processes during the regulation of skeletal muscle growth and mass." (PMID 25860951, 2015). "Furthermore, myostatin levels have been reported incats with congestive HF and hypertrophic cardiomyopathy." (PMID 39077334, 2024). "Although hypertrophic cardiomyopathy is characterized by an hypertrophied heart muscle while tricep samples were used in this study, our results suggest that the expression of genes in similar biological processes are altered by myostatin genotype regardless of activity level." (PMID 25710176, 2015).
leiomyoma (4 papers, 2013 to 2023). A well-circumscribed benign smooth muscle neoplasm characterized by the presence of spindle cells with cigar-shaped nuclei, interlacing fascicles, and a whorled pattern. "Another study on leiomyomas showed increased myostatin levels in cancer, but follistatin expression was unaffected compared to healthy controls." (PMID 36901894, 2023). "Additional studies suggest that activin A and MSTN act via the Smad signaling pathway on myometrial and leiomyoma cells." (PMID 35780124, 2022). "Activin A, MSTN, and follistatin-related genes were more abundant in human leiomyoma than in nearby human myometrium, although receptors, follistatin, and Smad7 mRNAs remained unaltered." (PMID 35780124, 2022). "Estrogens upregulate platelet-derived growth factor (PDGF) expression in leiomyoma cells, while they downregulate activin and myostatin in human myometrial explants." (PMID 24163697, 2013). "Furthermore, activin A and MSTN inhibited cell proliferation in primary myometrial cells but not in leiomyoma cells and decreased expression of proliferating cell nuclear antigen and Ki67 in myometrial cells was also detected." (PMID 35780124, 2022). "However, in both myometrial and leiomyoma cells, activin A and MSTN increase Smad2/3 signaling but do not influence ERK or p38 signaling, suggesting that activin A and MSTN can have antiproliferative and/or fibrotic effects on both cell types via Smad2/3 signaling." (PMID 35780124, 2022).
osteoarthritis (4 papers, 2020 to 2023). A noninflammatory degenerative joint disease occurring chiefly in older persons, characterized by degeneration of the articular cartilage, hypertrophy of bone at the margins and changes in the synovial membrane. "Furthermore, the inhibition of myostatin reduces bone destruction caused by osteoarthritis, so myostatin could be a target for treating osteoarthritis." (PMID 33536903, 2020). "The levels of serum myostatin and interleukin (IL)-1β were significantly elevated in synovial fluid from RA patients than that from osteoarthritis patients, immunohistochemistry data also revealed a positive correlation between myostatin and IL-1β, TNF-α." (PMID 36330524, 2022). "Patients with osteoarthritis have higher serum myostatin, which correlates with disease severity." (PMID 33854530, 2021).
prediabetes (4 papers, 2018 to 2026). "Prior to exercise training, those with RA, compared with those with prediabetes, had similar muscle cytokine concentrations but greater plasma galectin-3 and less skeletal muscle myostatin (P <0.05 for myostatin)." (PMID 30587230, 2018). "Exercise responses in muscle myostatin, cytokines, and body composition were significantly greater in prediabetes than in RA, consistent with impaired muscle remodeling in RA." (PMID 30587230, 2018). "Exercise training did not reduce mean concentration of galectin-3, muscle cytokines, or muscle myostatin in persons with either RA or prediabetes." (PMID 30587230, 2018). "However, the correlations of muscle remodeling markers (myostatin and cytokines) with favorable body composition outcomes were stronger in prediabetes than in RA." (PMID 30587230, 2018). "In contrast to our hypothesis, plasma galectin-3, skeletal muscle cytokines, and muscle myostatin were unaffected by 10 weeks of high-intensity interval training in persons with RA and prediabetes." (PMID 30587230, 2018). "To determine whether exercise training could improve remodeling, we measured changes in inter-relationships of plasma galectin-3, skeletal muscle cytokines, and muscle myostatin in patients with RA and prediabetes before and after a high-intensity interval training (HIIT) program." (PMID 30587230, 2018). "Moreover, in prediabetes but not in RA, myostatin was reduced in association with increased muscle mass." (PMID 30587230, 2018). "In prediabetes but not RA, body composition improvements correlated with reductions in muscle myostatin (r = −0.92; P <0.05; Fisher r-to-z P = 0.026)." (PMID 30587230, 2018). "Also, while exercise training did not reduce either group’s myostatin concentrations, myostatin responses were related to lean mass changes in prediabetes but not in RA." (PMID 30587230, 2018).
protein-energy malnutrition (4 papers, 2020 to 2025). A nutritional deficit that is caused by inadequate protein or calorie intake. "This type of investigation will not determine which factor, such as myostatin, adipokines, exercise, protein energy malnutrition and protein synthesis and breakdown, may play a role in this association." (PMID 32999391, 2020).
steatosis (4 papers, 2011 to 2024). Increased lipid within the cytoplasm of cells. "All 12 livers from control mice fed the high-fat diet received the highest steatosis score, whereas only 5 of 13 livers from myostatin-deficient mice received the highest score." (PMID 21390326, 2011). "The difference between control and myostatin-deficient mice in the distribution of steatosis scores was significant by Fisher's exact probability test (P<0.01)." (PMID 21390326, 2011). "The mean increase in liver mass in the obese myostatin-deficient mice (<0.1 g) was markedly attenuated compared with that of the obese mice with normal myostatin expression (0.5 g), and histology indicated that steatosis was not as severe in the myostatin-deficient mice." (PMID 21390326, 2011). "Our double mutant mouse model highlights the fact that hepatic steatosis seen earlier in the absence of beige fat can be rescued by the inactivation of myostatin." (PMID 33220490, 2021).